NOTCH1 (notch receptor 1)
Diseases named in the same sentence as NOTCH1 in open-access papers (continued):
Sharing a sentence is not in itself a finding about the gene and the disease.
tumor (continued). "Loss of NOTCH1 in this tissue leads to oral epithelial dysplasias and promotes tumor initiation while impairing barrier integrity and generating a wound-like environment in the underlying stroma (mesenchyme)." (PMID 31191362, 2019). "Combined POFUT1/NOTCH1 expressions were significantly associated with tumor issue site (p = 0.00004), pathologic stage (p = 0.00498) and histological type (p < 0.001)." (PMID 30380753, 2018). "The tumor suppressive role of NOTCH in epidermal differentiation was first identified in mice with keratinocyte-specific loss of Notch1 which developed skin carcinoma." (PMID 30087852, 2018). "Depending on context and tumor stage, aberrant NOTCH1 signaling has been directly linked to tumor suppressor or oncogene function." (PMID 30158530, 2018). "We cannot prove NOTCH1 or PIK3 subunit mutations evolved temporally from a lower grade tumor, causing its progression." (PMID 30417117, 2018). "Additional genes involved in Wnt/β-catenin signaling and/or Notch signaling, including Notch1 itself, were also downregulated in Ap4-deficient tumor organoids." (PMID 30177706, 2018). "NOTCH1 expression was significantly associated with tumor issue site (p = 0.00099) and overexpressed in 70.9% of colon and 84% of rectum tissues." (PMID 30380753, 2018). "Using conditional Notch1 KO mice, we showed that loss of Notch1 in tumor cells delays AKT/Yap-induced tumor development and mildly reduces the levels of a subset of Notch target genes." (PMID 29545603, 2018). "Aberrant Notch1 activation has been shown to be a predictor of poor prognosis in HCC patients due to Notch1-Snail1 signaling associated with tumor metastasis." (PMID 30405889, 2018). "Conversely, loss of function mutations in NOTCH1/2/3 have also been identified suggesting NOTCH can also function as a tumor suppressor." (PMID 30967879, 2018). "Exome sequencing of Tet2−/− tumours reveals accumulation of numerous mutations, including Apc, Nf1, Flt3, Cbl, Notch1 and Mll2, which are recurrently deleted/mutated in human haematological malignancies." (PMID 28440315, 2017). "In humans, expression of Notch1 has been positively associated with depth of invasion, lymph node metastases and tumor-node-metastasis (TNM) stage." (PMID 29104587, 2017). "Since our studies revealed Hes-1 as one of most deregulated genes in ATL SP cells and NOTCH1 signaling has been implicated in ATL tumor growth in vitro and in vivo, we next investigated the role of NOTCH1 signaling in SP cells maintenance." (PMID 28920078, 2017). "We previously showed in the AOM-DSS mouse model a loss of Notch1 signalling during CAC development partially counteracted by EPA-FFA supporting a tumor-suppressor role of this pathway during inflammation-induced intestinal tumorigenesis." (PMID 28785079, 2017). "As an oncogene, Notch1 was found increased in many kinds of malignant tumors and associated with tumor cell proliferation, invasion and metastasis." (PMID 27705934, 2017). "We observed that miR-34a overexpression significantly suppressed tumor growth, reduced the expression of Notch1, and reversed the EMT-associated phenotypes." (PMID 29340051, 2017). "Larger tumor size (>5 cm), metastasis positive, and micro vascular invasion positive were features that were associated with over-expression in Notch 1 according to the clinicopathological features." (PMID 29093570, 2017). "Larger tumor size (>5 cm), metastasis positive, micro vascular invasion positive features were associated with an increase in Notch 1 expression according to clinicopathological features." (PMID 29093570, 2017). "HER2 status, number of metastatic sites and tumor size at diagnosis were negatively associated with NOTCH1 mutations in multiple regression analysis." (PMID 28729728, 2017).
tumor (continued). "Since the Pim inhibitor DHPCC-9 and the S2152A mutation in Notch1 reduce Notch activity and tumor growth to a similar extent, this suggests that Pim kinases are the major kinases targeting Ser2152 of Notch1 in both MCF-7 and PC-3 cells." (PMID 27281612, 2016). "The overall frequency of tumor samples with NOTCH1 or PIK3CA mutations in cohort #1 or #2 was statistically higher than that of cohort #3 or #4." (PMID 26528858, 2016). "Tumour-associated NOTCH1 mutations were identified in three of our OSCC lines via whole exome sequencing." (PMID 27693639, 2016). "Exome sequencing of HNSCC strongly implicated NOTCH1 as a tumor suppressor in this malignancy, as close to 40 % (11/28) of NOTCH1 mutations were truncating mutations predicted to be inactivating." (PMID 29034103, 2016). "GSEA analysis further confirmed loss of Notch1 signalling in Ptenpc−/− tumours treated with PF-03084014." (PMID 27941799, 2016). "Nrf2, Keap1, and Notch1 rank among the first frequently mutated genes in tumors and were deemed to be significant both in the combined sets of tumors and in individual tumor types." (PMID 27847554, 2016). "We showed that efficiency of CO is directly linked to signaling through Erk1/2 and Notch1 pathways in tumor stroma." (PMID 26993595, 2016). "In a model of small cell lung cancer Sriuranpong and colleagues demonstrated that the overexpression of the active forms of Notch1 and Notch2 causes the block of cell cycle at G1 phase and the arrest of the tumor growth." (PMID 27929540, 2016). "By whole‐exome sequencing of 74 HNSCC tumor‐normal pairs 6, mutations of NOTCH1, NOTCH2, and NOTCH3 were identified in 14%, 5%, and 4% of HNSCC samples." (PMID 27228302, 2016). "In the majority of the tumor cell line types, mutations were found in at least three different Notch receptor genes, but with liver as a notable exception, where only NOTCH1 and NOTCH4 were found to be mutated." (PMID 25907971, 2015). "As Notch1 expression is associated with tumor stage, we evaluated the expression of Hes1 in human CRC tissues." (PMID 26650241, 2015). "ITCH’s targets, including p63, p73, and Notch1, are usually associated with tumor formation and chemosensitivity, demonstrating the connection of ITCH to cancer biology." (PMID 26110611, 2015). "It will be interesting to use the Notch1-CreERT2SAT mice described here to specifically induce oncogenic mutations in ERαneg luminal progenitors and determine if this can influence the tumor outcome." (PMID 25688859, 2015). "Together our results suggest that the loss of Postn is accompanied by reduced Notch1 activity and a failure to support tumor growth at secondary sites." (PMID 25592291, 2015). "Latterly, ITCH was found to be crucial in the control of proteasome degradation of several important substrates such as p63, p73, Notch1, and Dvl2; all of which are usually associated with tumor formation and chemosensitivity." (PMID 25749389, 2015). "Totally, 18 studies have assessed the association between Notch1 expression and tumor clinicopathological features." (PMID 26121683, 2015). "Previous studies showed that inhibition of Notch1 via suppression of γ-secretase activity reduces c-Myc and Hes1 levels, which was associated with decreased tumor cell proliferation." (PMID 25879451, 2015).
tumor (continued). "Elevated levels of Notch-1, 3 and their ligand Jagged 1–4 expressions were found to be associated with tumor progression and predicted poor prognosis in NSCLC, suggesting a promising biomarker for NSCLC." (PMID 25477004, 2014). "After adjusting for age, gender, tumor size, tumor grading, and tumor stage, multivariate analyses showed that NOTCH1 expression was an independent risk factor for survival." (PMID 25149074, 2014). "Notch1 is involved in migration and invasion of tumor cells, and an elevated Notch1 protein is associated with poor outcome." (PMID 25420528, 2014). "Here we provided further evidence supporting these views and implicated that altered Notch1 expression in human colorectal tissues increased the propensity for tumor formation." (PMID 24312514, 2013). "Building on these validation studies, we next used IHC to screen a series of FPE human cancers for evidence of NOTCH1 activation, focusing on tumor types in which NOTCH1 gain-of-function mutations have been described." (PMID 23825651, 2013). "NICD1 staining was somewhat stronger in the earlier tumor with mutated NOTCH1, but both biopsies showed diffusely positive NICD1 staining." (PMID 23825651, 2013). "In contrast, we found increased NOTCH1 expression in all Fli-1 T cells and detected Notch1 mutations in all tumours." (PMID 23667468, 2013). "Sprouting angiogenesis is a hallmark of tumor neovascularization, and Dll4/Notch1 signaling functions to inhibit vessel sprouting." (PMID 23601498, 2013). "NOTCH1 has been associated with “stemness” properties, as well as with the differentiation of cancer stem cells (tumor stem-like cells) into endothelial progenitor cells." (PMID 23586024, 2013). "To develop a reliable staining method for NICD1, we made use of control FPE tissues from mice xenografted with human tumor cell lines bearing oncogenic NOTCH1 mutations that result in ligand-independent generation of NICD1." (PMID 23825651, 2013). "Using the γ-secretase inhibitor DAPT, a potent Notch1 inhibitor, clear loss of survival and proliferation was observed in Tcf1−/− tumor cells." (PMID 23185135, 2012). "Sequence analyses of the HD and PEST regions in Notch1 transcripts expressed in Id1 tumor samples revealed such mutations at frequencies of 17% and 60% respectively." (PMID 22393458, 2012). "Here we show that the transcription of the gene encoding eIF6 is modulated by the receptor Notch-1, a protein involved in embryonic development and cell differentiation, as well as in many neoplasms." (PMID 22348144, 2012). "Histological analysis of tumors treated with DLL4/NOTCH1 inhibitors has revealed that the reduced tumor growth is associated with an apparent increase in tumor vascular density." (PMID 21824400, 2011). "Lymphangiogenetic characteristics and their associations with NF-κB and Notch1 signaling were also measured to determine the contribution of NF-κB and Notch signaling to tumor-induced lymphangiogenesis." (PMID 21939555, 2011). "It is noteworthy that a parallel study in childhood ependymomas has shown an association between tumor recurrence and frequent amplification of the 9qter, precisely at the location of both NOTCH1 and TNC genes." (PMID 21078177, 2010). "On the other hand, dysregulation of Notch1 signaling is associated with many different types of cancer as well as tumor angiogenesis, making Notch1 a potential therapeutic target." (PMID 20161710, 2010). "In specific cell types like keratinocytes, Notch signaling plays an important pro-differentiation and tumor suppressing function, with down-modulation of the Notch1 gene being associated with cancer development." (PMID 20442780, 2010).
tumor (continued). "Higher Notch-1 levels correlated with progressively abbreviated overall survival, and with increased expression of survivin, a tumor-associated cell death and mitotic regulator implicated in stem cell viability." (PMID 19025652, 2008). "Interestingly, the median of tumor mutational burden for NOTCH1 mutated tumors was significantly higher than for NOTCH1 wild-type tumors, because of the alterations in DNA damage and repair-related genes." (PMID 40563292, 2025). "Notch‐1 activation could promote orthotopic tumour growth but cause lower tumour metastasis, which is an interesting direction for the future studies." (PMID 39343985, 2025). "Notably, 70% of plasma samples harbored NOTCH1 mutations, a frequency significantly higher than the 20% observed in tumor tissues." (PMID 40563292, 2025). "Concerning clinically relevant subgroups, we observed that NOTCH1 mRNA overexpression was associated with a significantly less favourable outcome in patients with HR-positive/HER2-negative tumours getting adjuvant chemotherapy (adjusted hazard ratio 3.6, 95% CI 1.16–11.17, p = 0.027)." (PMID 39153127, 2025). "Conversely, loss-of-function mutations in NOTCH1 (where it acts as a tumor suppressor) may lead to hyperactivation of the NF-κB signaling pathway, resulting in upregulated PD-L1 expression." (PMID 41488620, 2025). "While upregulation of NOTCH1 and its associated pathway components is commonly observed during the progression from normal mucosa to carcinoma, its influence on tumor differentiation, metastasis, and prognosis appears to vary across anatomical sites and tumor subtypes." (PMID 41465166, 2025). "Alterations of NOTCH1, a gene involved with cell differentiation and stem cells’ maintenance, highlight the context-dependent duality of genetic mutations in tumorigenesis (tumor promoter versus tumor suppressor activity) depending on cellular environment." (PMID 41374467, 2025). "Based on these results, we conclude that Notch1 mutation may have a tumor‐suppressive role in OSCC cell lines." (PMID 41026775, 2025). "The present study aimed to investigate the interaction between Notch1 mutations and PD‐L1 expression, which may enhance anti‐tumor immunity." (PMID 41026775, 2025). "Additionally, high Notch1 expression showed significant associations with deeper tumor invasion, lymph node metastasis, advanced tumor stage, metastasis, and shorter overall survival—corroborating the work of other researchers." (PMID 40060224, 2025). "Notch1 showed a significant association with tumor depth (p = 0.035)." (PMID 41027955, 2025). "Furthermore, signaling from CAFs can modulate the plasticity of CSCs, e.g., the pathway Notch1 from tumor-associated fibroblasts acts as a stem phenotype switch." (PMID 40806546, 2025). "This study focused on the tumor immunology associated with Notch1 mutations in OSCC." (PMID 41026775, 2025). "Moreover, pan-cancer analyses have revealed recurrent co-mutations in KEAP1, NFE2L2, and NOTCH1, supporting a cooperative role in driving tumor progression." (PMID 40563292, 2025). "Leptin is another factor implicated in tumor growth via activation of Notch1 effectors." (PMID 40942013, 2025).
tumor (continued). "Based on these observations, we recently hypothesized that the interplay between Notch1 mutation and PD‐L1 expression could reprogram the tumor microenvironment (TME) and influence CD8+ T cell infiltration." (PMID 41026775, 2025). "Finally, the FGF/FGFR1/NOTCH1 within RB1 variant group has a remarkably high ratio of inner‐tumor CD8+ T cell infiltration, non‐exhausted T cells, exhausted TCD8+PD‐1+LAG3− cells, and TRMCD8+CD69+CD103+cells." (PMID 40001320, 2025). "In the present study, we highlighted this recent finding that the Notch signaling pathway influences PD‐L1 and CD8+ T cells in the tumor immune microenvironment, which may provide insight into a similar mechanism associated with Notch1 mutation." (PMID 41026775, 2025). "In cancer, the loss of miR-34a expression contributes to tumor progression by allowing the upregulation of oncogenes such as Notch1 (Notch Receptor 1), c-MYC (Cellular myelocytomatosis oncogene), and BCL2 (B cell lymphoma 2), all of which promote cell survival and proliferation." (PMID 40260417, 2025). "Unfortunately, targeting Notch1 simultaneously poses significant risks, such as gastrointestinal toxicity, diminishment of normal stem cell populations and increased risk of cancers in which Notch1 acts as a tumor suppressor." (PMID 39172098, 2024). "Together, this indicates that loss of wild-type Kras with epithelial NOTCH1 activation in KPN tumours activates Wnt, restricts the TGFβ mediated neutrophil recruitment required to generate an immunosuppressive, pro-metastatic niche and blunts the metastases of tumours lacking wild-type Kras." (PMID 38168062, 2024). "Notch1, the first Notch receptor discovered in mammals, exhibits heightened expression in various tumors, closely associated with increased cancer stem cells, tumor invasion, metastasis, and drug resistance." (PMID 38866828, 2024). "This opposite result may be caused by the different expression levels of Notch-1 protein in different tumor cells and different stages of tumor development." (PMID 39691600, 2024). "We next queried whether NOTCH1 signalling was dysregulated within tumour cells, especially given the genomic disruption in each tumour of one allele of NRARP, the negative regulator of NOTCH1." (PMID 37749094, 2023). "INACTIVATE NOTCH1 inactivating mutations are present in 11-19% of HNSCC, suggesting that NOTCH1 may behave as a tumor suppressor in contrast to its proto-oncogenic role in other cancers." (PMID 37008245, 2023). "Others, including HD and PEST mutations found in patients, generate weaker NOTCH1 mutant forms that complement other leukemogenic signals or require cooperation with additional oncogenic pathways or with loss-of-function tumor suppressor mutants for driving T-cell transformation." (PMID 36674902, 2023). "Patient 27 acquired a Notch1 mutation at the time of tumor recurrence." (PMID 37533228, 2023). "That is, high VAFs, including NOTCH1, indicate that clonal expansion in the elderly may result in a predisposition to tumor formation and progression." (PMID 37968650, 2023). "Even more, the mutation rate of NOTCH1 in esophagus is higher than that in tumor tissues." (PMID 36991467, 2023). "Moreover, NOTCH1 operates as a dominant cancer gene (oncogene) in a variety of neoplasms through mutations encompassing rearrangements, point mutations and indels." (PMID 37749094, 2023). "NOTCH1-2’s downregulated expression was also linked with residual tumour after surgery." (PMID 36982928, 2023). "We speculate that the Notch1 mutation is not only a driver gene, but also may contribute to tumor progression and recurrence." (PMID 37533228, 2023). "The differential expression of NOTCH1 in different regions of the tumor and its association with GSCs could provide valuable insights into the tumor’s heterogeneity and stem cell population." (PMID 37593751, 2023).